GLS (glutaminase)
Diseases named in the same sentence as GLS in open-access papers (continued):
Sharing a sentence is not in itself a finding about the gene and the disease.
cancer (continued). "MYC has previously been described to regulate GLS which redirects glutamine pools into the Krebs cycle in cancer cells." (PMID 34399819, 2021). "IDHm cells are thus reliant on glutamate synthesis from glutamine and are particularly sensitive to GLS inhibition in combination with oxidative stress–inducing radiation, revealing a unique therapeutic point of leverage for treating IDHm cancers." (PMID 34109280, 2021). "In further support of this, N-acetyl cysteine (NAC) largely rescues cell death in SLC7A11high cancer cells under glucose starvation, but does not rescue the growth defect of these cells upon glutamine deprivation or glutaminase inhibition." (PMID 33000412, 2021). "Alterations to metabolic pathways have recently attracted great interest as possible cancer treatments and many studies have reported that targeting glutaminase is an ideal approach in many cancers." (PMID 33513833, 2021). "The heightened dependency on glutamine metabolism renders cancer cells sensitive to inhibition of GLS activity, making GLS an attractive target for cancer therapeutics." (PMID 34731180, 2021). "Glutaminase, an enzyme which converts glutamine to glutamate, was found to be frequently upregulated in cancer cells." (PMID 33672144, 2021). "Several GLS inhibitors have been developed based on the crucial functions of GLS in various cancer types that are driven by the dysregulated glutamine metabolism." (PMID 34354052, 2021). "In this study, we showed the tumor-suppressive function of EZH2 was mediated by inhibiting the expression of GLS, which played a vital role in cancer metabolic reprogramming." (PMID 34671029, 2021). "Mechanistically, inhibition of glutaminase (GLS), the first enzyme for Gln anaplerosis, sensitizes cancer cells to DNA damage by inducing amphiregulin (AREG) that promotes apoptotic cell death." (PMID 34924566, 2021). "As a result of the high activity and expression of glutaminase, cancer cells present a higher rate of conversion of glutamine into glutamate." (PMID 34944392, 2021). "Glutaminase (GLS) has been explored as a therapeutic cancer target, and its inhibition also results in increased sensitivity of tumor cells to chemotherapeutic agents." (PMID 34354052, 2021). "It has been well established that glutamine synthesis is upregulated in most cancers, including BC, and consequently, glutaminase catalytic activity and levels are upregulated." (PMID 34439127, 2021). "Studies on metabolic reprogramming, which targets glutamine metabolism in cancer cells, have focused on the glutaminase isozyme GLS." (PMID 34235071, 2021). "CB‐839 is a highly selective inhibitor of GLS and is currently in clinical trials for treating several cancer types in combination with other therapeutics." (PMID 34075648, 2021). "Several studies demonstrate that glutaminase contributes to cancer tumour growth in various human cancers such as prostate, lung and colorectal." (PMID 34439127, 2021). "Many NSCLC cell lines differ in their sensitivity to glutaminase inhibitors, making it particularly important to determine the metabolic profile under which they can be efficacious against cancer cells." (PMID 35223460, 2021). "Treatment of KPC cell lines with CB-839 in the background of DEM reduced the viability of these cells, suggesting that induction of Nrf2 activation sensitized KPC cancer cells to glutaminase inhibition." (PMID 33672789, 2021). "Co-targeting glutamine synthetase in stroma and glutaminase in cancer cells reduces tumor weight, nodules, and metastasis." (PMID 34631530, 2021). "In this study, we wanted to know the role of an enzyme, glutaminase, which is a substance produced by the body that breaks down glutamine so it can be used by cancers to grow." (PMID 34439127, 2021). "Recent studies have shown that GLS is highly expressed in some malignant tumors and knockdown of GLS significantly reduces the invasion and proliferation of cancer cells, indicating the cancer-promoting role of GLS." (PMID 33849550, 2021).
cancer (continued). "A meta-analysis of most human cancers (considered by these authors) revealed a high ratio of PPAT/Glutaminase 1 (GLS1), which correlated with cancer prognosis." (PMID 33854965, 2021). "We found that GLS inhibition or Gln deprivation-induced AREG expression in cancer cell lines including HeLa and HCT116, which was reversed by DMKG treatment." (PMID 34924566, 2021). "The oncogenic transcription factor c-Myc promotes glutaminolysis to stimulate the growth and proliferation of cancer cells through upregulation of glutaminase (GLS)." (PMID 33808242, 2021). "High expression levels of glutaminase (GLS1) are reported for several cancers, and correlate with parameters of disease status." (PMID 33947068, 2021). "In another study, ammonia significantly increased the expression of GDH and GLS in metastatic hepatocellular carcinoma Hep3B cancer cells." (PMID 34503536, 2021). "GLS is the main isoform expressed in cancer cells, and there is increasing evidence suggesting it plays an important role in carcinogenesis and tumour progression in various solid cancers." (PMID 34439127, 2021). "To confirm that oxidative stress-induced activation of Nrf2 was sufficient to sensitize cancer cells to glutaminase inhibition, we treated KPC cell lines with the Nrf2 inducer, DEM." (PMID 33672789, 2021). "The enzyme also possesses off-target residual glutaminase activity and several studies have indicated that both its asparaginase and glutaminase activity are required for antileukemic efficacy depending on the expression of ASNS by the cancer." (PMID 34277440, 2021). "Glutaminase 1 (GLS1) catalyzes the first step in glutamine metabolism in the conversion of glutamine to glutamate and ammonia and is frequently overexpressed in cancers." (PMID 33803326, 2021). "As a key enzyme of glutamine metabolism, GLS functions as a cancer driver and can also be a therapeutic target in cancer." (PMID 34671029, 2021). "We blocked the tumor anabolism with orlistat, lonidamine and DON (6-Diazo-5-oxo-L-norleucine) (OLD drug scheme) to inhibit FASN, HK2 and GLS, respectively, whereas with the combination of anti-catabolic drugs we aimed to ameliorate cancer cachexia." (PMID 33664364, 2021). "Targeting glutaminolysis via glutaminase inhibition emerges as a promising strategy to disrupt cancer metabolism and tumor progression." (PMID 33194749, 2020). "Identification of glutaminase inhibitor sensitive cancers and optimization of combination therapies would be an interesting focus for targeting glutaminolysis in a variety of cancers." (PMID 33194749, 2020). "Glutaminase is dysregulated in many cancers, which makes it an appealing target for cancer therapies." (PMID 33194749, 2020). "GLS-1 has been found to be upregulated in some cancers, and in some cases deregulated glutamine metabolism is essential for cancer growth." (PMID 32150977, 2020). "Glutaminase inhibitor CB-839, a potent and selective inhibitor of glutaminase, is currently in 1/2 clinical phase trails for malignant tumors, including TNBC." (PMID 32296646, 2020). "The c-Myc suppression of miR-23a/b leads to the enhancement of glutaminase-regulating glutamine metabolism, a process that is paramount for the bioenergetics and maintaining the redox homeostasis in cancer cells." (PMID 32559232, 2020). "CAF-derived lactate, in turn, promotes OXPHOS in cancer cells, favors Gln uptake and catabolism and is responsible for the resistance to glutaminase inhibitors." (PMID 32486505, 2020). "While GLS upregulation correlates with proliferating stages and malignancy in many types of cancer and experimental tumors, little is known about the role of GLS2 in tumorigenesis." (PMID 32042057, 2020). "Recently, the strategy of cancer therapy in glutamine metabolism inhibition has begun to concentrate on glutamine deprivation, glutaminase blocking, and membrane glutamine transporter inhibition." (PMID 33510635, 2020).
cancer (continued). "Here, we review the regulation of glutaminase and the role of glutaminase in cancer metabolism and metastasis." (PMID 33194749, 2020). "CB-839 is a novel glutaminase inhibitor that is currently being evaluated in several clinical trials to test its anti-carcinogenic properties in patients, as it effectively kills cancer cells in in vitro and in vivo models." (PMID 33187083, 2020). "Taken together, GLS inhibitors have shown great pre-clinical promise across cancers; however, resistance is a major hurdle of monotherapy regimes." (PMID 32937954, 2020). "This important role of glutaminase in glutamine metabolism makes it a valuable target for cancer therapy." (PMID 33194749, 2020). "In human cancer organoids and in in vivo model it was described that the administration of metformin and a glutaminase inhibitor (GLSi), which blocks Gln consumption, efficiently overcome metformin resistance." (PMID 32486505, 2020). "Apart from asparaginase, arginine deiminase, arginase, some other amino acid enzymes have been recently developed for cancer therapy, including methionase, lysine oxidase, phenylalanine ammonia lyase, and glutaminase." (PMID 33510635, 2020). "Another glutaminase inhibitor (CB-839) was also reported to induce selective radio-sensitivity in IDH mutant cancers and terminal differentiation in IDH mutant AML." (PMID 32825279, 2020). "GLS activity has been shown to be critical for most cancer cell growth, at least in monolayer culture." (PMID 31980738, 2020). "Glutaminase (GA) catalyzes the first step in mitochondrial glutaminolysis playing a key role in cancer metabolic reprogramming." (PMID 32042057, 2020). "Despite the promising cell proliferation inhibition results observed in vitro, some cancer cells show resistance to glutaminase inhibitors." (PMID 33194749, 2020). "Blocking glutaminase to halt the conversion of glutamine to glutamic acid facilitates cancer cell apoptosis by reducing glutathione levels (a glutamic acid derivative), leading to reactive oxygen species generation." (PMID 33374949, 2020). "Several lines of evidence have demonstrated utility of glutaminase inhibitors as anticancer agents in a variety of cancer types including breast cancer, lung cancer, pancreatic cancer, melanoma, and hematological malignancies." (PMID 32266129, 2020). "In this review, we focus on the current understanding of glutaminase-related glutaminolysis in cancer metabolism." (PMID 33194749, 2020). "This fact has been clearly demonstrated in recent studies, where inhibition of cancer proliferation and reversion of the malignant phenotype were achieved by knocking-down GLS or by upregulation of GLS2 expression." (PMID 32042057, 2020). "Inhibiting GLS has been a successful therapeutic strategy in a variety of cancers that are addicted to Gln." (PMID 33101674, 2020). "This is in line with previous research showing that upregulation of αKG-dependent Gln metabolism and increased GLS expression promotes the maintenance of cancer stem cells through various mechanisms." (PMID 32337072, 2020). "Although as a promising therapeutic approach to combat cancer, limited clinical research data of glutaminase inhibition is available." (PMID 33194749, 2020). "Particular cancer types, such as TNBC, are also associated with elevated GLS expression and glutamine dependency." (PMID 33092283, 2020). "In this review, we updated the current understanding of glutaminolysis in cancer from the view of glutaminase isoenzymes and summarized the glutaminase inhibitor based therapeutic strategies." (PMID 33194749, 2020). "By downregulating miR-23, which suppresses glutaminase (GLS), Myc can upregulate GLS and enhance glutamine metabolism in cancer cells." (PMID 32610612, 2020). "Cancer cells grown in vitro display different levels of sensitivity to glutaminase inhibition depending on culture medium composition." (PMID 32450839, 2020).
cancer (continued). "Glutaminase inhibitors have been shown to reduce tumor burden, and among the inhibitors, CB-839, the most advanced, is in clinical trials for multiple cancer types as a combination therapy." (PMID 31980738, 2020). "Cancer cells usually up-regulate the expression of glutaminase that catalyzes the first step of glutamine degradation (glutaminolysis)." (PMID 32708822, 2020). "Blocking glutamate production from glutamine by GLS inhibition will down-regulate this important antioxidant pathway, resulting in higher ROS levels, which will be selectively toxic to cancer cells due to their increased local ROS levels." (PMID 33014794, 2020). "For example, c-MYC activates the expression of ASCT2 and GLS-1 under the induction of lactic acid, leading to elevated glutamine uptake and catabolism in cancer cells." (PMID 33489906, 2020). "In this context, we evaluated the significance of glutaminase expression in various human cancers using a number of online bioinformatics platforms and tools." (PMID 30871151, 2019). "Increased glutaminolysis and/or increased levels of GLS have been found in a number of cancers that become resistant to other therapies." (PMID 31817676, 2019). "Glutaminase is an example of such an enzyme, the activity of which is noticeably dysregulated in several cancer cells." (PMID 30871151, 2019). "Although these compounds exhibit both increased specificity against GLS isoforms and antitumor effects on several cancer cell lines, their hydrophobic nature still hinders their application in vivo." (PMID 31429768, 2019). "Compared with their expression levels in normal tissues, both glutaminase members were highly upregulated in certain cancers and upregulated to a lesser extent in others." (PMID 30871151, 2019). "Myc promotes glutaminolysis via induction of GLS expression at the transcriptional level in cancer cells." (PMID 30910998, 2019). "High extracellular cystine can drive glutaminase activity by depleting the intracellular glutamate pool, thus making cancer cells more dependent on glutaminase to replenish intracellular glutamate." (PMID 31096630, 2019). "It has been reported that GLS expression or catalytic activity is regulated by a variety of oncogenes and survival signals in cancer cells at the multiple levels." (PMID 30910998, 2019). "Glutaminase inhibitors target cancer cells by blocking the conversion of glutamine to glutamate, thereby potentially interfering with anaplerosis and synthesis of amino acids and glutathione." (PMID 31088535, 2019). "Glutaminase activity has been demonstrated to be critical for the growth of most cancer cells in culture, and several inhibitors of glutaminase have been developed." (PMID 31096630, 2019). "GLS is overexpressed in cancer cells and consequently ammonia levels are higher in tumours than normal tissue." (PMID 30646605, 2019). "Glutaminase (GLS), a crucial enzyme involved in the regulation of glutamine metabolism, has been reported to play crucial roles in cancer development." (PMID 31196962, 2019). "Glutaminase 1 (GLS1) was traditionally known as a mitochondrial enzyme that hydrolyzes glutamine into glutamate and fuels rapid proliferation of cancer cells." (PMID 30674873, 2019). "Glutamate m + 5 was labeled faster in mitochondria, suggesting that mitochondrial glutaminase is the prime route for glutamate production from glutamine, in accordance with the known localization of this enzymatic activity in cancer cells." (PMID 30903027, 2019). "It has been shown that asparaginase also has glutaminase activity, which can kill cancer cells, raising the question of how important glutamine depletion is to the induction of leukaemic cell death." (PMID 30578463, 2019). "The impact of the methylation of glutaminase promoter on certain types of cancer has been previously examined." (PMID 30871151, 2019). "Next, glutamine is converted into glutamate thanks to the GLS enzyme activity, which is also upregulated in many cancers." (PMID 31744229, 2019).
cancer (continued). "The expression patterns of GLS2 in different types of cancer are substantially different from that of GLS." (PMID 30871151, 2019). "For each glutaminase member, we selected a set of the top four types of cancer based on the respective overexpression nature of that gene." (PMID 30871151, 2019). "While these glutaminase inhibitors are effective against most cancer cells grown in culture, often times they are less effective in mouse models of cancer." (PMID 31096630, 2019). "We demonstrated that the uptake of glutamine by amino acid transporter (SLC1A5), as well the metabolism of glutamine to glutamate by glutaminase (GLS) was upregulated in the cancer epithelia in response to elevated concentrations of glutamine in the media." (PMID 31627186, 2019). "Cancer cells use the enzyme glutaminase to convert glutamine to glutamate, and to form precursors for the processes of anaplerosis, glutathione synthesis, and fatty acid production, which allow for tumorigenesis." (PMID 31311965, 2019). "Combined treatment with the glutaminase inhibitor CB-839 and mTOR inhibitors shows efficacy in overcoming therapeutic resistance to other targeted inhibitors in these different types of cancer." (PMID 31817676, 2019). "GLS is already a cancer metabolism drug target—the GLS inhibitor CB-839 is currently being used in clinical trials to treat certain types of solid and hematological malignancies that also rely on GLS activity." (PMID 31319842, 2019). "For example, c-MYC stimulates glutamine catabolism to fuel growth and proliferation of cancer cells through up-regulating GLS." (PMID 31196962, 2019). "We then determined the genes correlated with GLS and GLS2 in certain types of cancers in which these glutaminase members are significantly upregulated using the R2 platform." (PMID 30871151, 2019). "The targeting of glutamine metabolism specifically via pharmacological inhibition of glutaminase 1 (GLS1) has been translated into clinical trials as a novel therapy for several cancers." (PMID 31231915, 2019). "The glutaminase inhibition of glutamine-addicted cancer cells leads to the disruption of metabolic pathways, such as macromolecule synthesis, ATP production, and the intracellular redox balance." (PMID 31357507, 2019). "Glutaminase inhibitor CB839 exhibited a more notable impact on the growth of RET-aberrant cancer cells." (PMID 31221965, 2019). "GLS has been proposed as a therapeutic target in many cancers and clinical trials of glutaminase inhibitors are ongoing, including for patients with GBM (NCT03875313)." (PMID 31450721, 2019). "As such, next, we determine which types of cancer were connected with significant CNAs in the glutaminase-gene signature using cBioPortal." (PMID 30871151, 2019). "This study highlights the potential efficacy of a combination therapeutic strategy in targeting cancer growth, and identifies a potential resistance mechanism to ongoing clinical trials that use glutaminase inhibitors." (PMID 30478303, 2018). "Overexpression of glutaminase (GLS1) in cancer cells and a subsequent increase of amino acids production have been reported in ER-negative breast cancer, with apparent association to poor prognosis." (PMID 29562706, 2018). "Here, we have shown that NSCLC cells exhibit much higher glutaminase activity than normal human bronchial epithelial (HBE) cells and the high glutaminase activity in the cancer cells results from GAC phosphorylation." (PMID 29515166, 2018). "Here, we report that phosphorylation is a crucial post-translational modification of GAC, which is responsible for the higher glutaminase activity in lung tumor tissues and cancer cells." (PMID 29515166, 2018). "It was shown that cancer cells cultured in media that better represent in vivo conditions exhibit less glutamine metabolism and are less sensitive to glutaminase inhibition than the same cancer cells cultured in standard cell culture media." (PMID 29764521, 2018).